NOTO (notochord homeobox)
Description:
Transcription regulator acting downstream of both FOXA2 and Brachyury (T) during notochord development. Required for node morphogenesis. Is essential for cilia formation in the posterior notochord (PNC) and for left-right patterning; acts upstream of FOXJ1 and RFX3 in this process and is required for the expression of various components important for axonemal assembly and function. Plays a role in regulating axial versus paraxial cell fate. Activates the transcription of ciliary proteins C11orf97 homolog, FAM183B and SPACA9 in the embryonic ventral node (By similarity).
Tractability: No criterion of Open Targets' tractability assessment is met for any kind of drug.
Gene: Protein-coding gene on chromosome 2 (73,202,574 to 73,212,513, forward strand). Ensembl gene ENSG00000214513.
Subcellular location: Nucleus
Subcellular location (Human Protein Atlas): Nucleoplasm; Cytosol
Pathways (Reactome):
Developmental Biology: Formation of axial mesoderm
Gene Ontology:
Molecular function: protein binding; sequence-specific double-stranded DNA binding; DNA-binding transcription factor activity, RNA polymerase II-specific; RNA polymerase II cis-regulatory region sequence-specific DNA binding; DNA binding
Biological process: brain development; central nervous system development; neuron differentiation; regulation of transcription by RNA polymerase II
Cellular component: chromatin; nucleus
Genetic constraint (gnomAD): Loss-of-function variants: 19 observed, 17.38 expected, observed/expected ratio (o/e) 1.09, 90% interval 0.76 to 1.6. The upper end of that interval is the gene's LOEUF score, 1.6, which puts it in group 6 of 6, group 1 being the genes least tolerant of losing a copy. Missense variants: 367 observed, 291.06 expected, observed/expected ratio (o/e) 1.26, 90% interval 1.16 to 1.38. Synonymous variants: 150 observed, 126.3 expected, observed/expected ratio (o/e) 1.19, 90% interval 1.04 to 1.36.
Homologues: Orthologues: chimpanzee NOTO (99% identical), macaque NOTO (92% identical), rabbit NOTO (69% identical), pig NOTO (64% identical), mouse Noto (55% identical), dog NOTO (53% identical), guinea pig NOTO (53% identical), rat Noto (52% identical), Drosophila melanogaster CG18599 (24% identical), zebrafish noto (24% identical), Caenorhabditis elegans ceh-5 (15% identical). Paralogues in human: GSX1 (22% identical).
Diseases named in the same sentence as NOTO in open-access papers:
NOTO is named in the same sentence as 1 disease in open-access papers, as found by Europe PMC text mining. Sharing a sentence is not in itself a finding about the gene and the disease.
NOTO shares sentences with these, for which no sentence is quoted: age (1 paper).